FAP (fibroblast activation protein alpha)
Diseases named in the same sentence as FAP in open-access papers (continued):
Sharing a sentence is not in itself a finding about the gene and the disease.
melanoma (continued). "In two mouse melanoma models, depleting FAP+ stroma cells from the tumor microenvironment (TME) upon vaccination with an adenoviral-vector reduces frequencies and functions of ISCs." (PMID 26943036, 2016). "Here, we report that A2BR blockade in melanoma-bearing mice reduces the number of fibroblast activation protein (FAP)-positive stromal cells in tumor lesions." (PMID 27590504, 2016). "Here we show that A2BR stimulation enhances the number of FAP positive cells in melanoma tissues of C57Bl6 mice." (PMID 27590504, 2016). "Both sets of data confirm that targeting FAP+ tumor stroma cells results in significantly prolonged survival of melanoma-bearing mice." (PMID 26943036, 2016). "We demonstrated that FAP α vaccine combined with curcumin lavage inhibits tumor growth and prolongs the survival of mice implanted with melanoma cells." (PMID 26985769, 2016). "We examined the expression of FAP in melanoma sections harvested from mice treated with the selective A2BR agonist Bay60-6583 or vehicle." (PMID 27590504, 2016). "The number of FAP positive cells was significantly increased in melanoma tissues of mice treated with Bay60-6583 compared to control." (PMID 27590504, 2016). "In this context and of particular importance, the formation of a complex composed of integrin α3β1 and FAP on the cell surface has been demonstrated to be necessary for the formation of functional invadopodia on melanoma cells." (PMID 25600705, 2015). "In our research, we found that FAPα is stably expressed by the tumor stromal cells in B16 melanoma-bearing mice." (PMID 26305550, 2015). "A FAP-positive SK-Mel-187 melanoma xenograft and an NCI-H69 xenograft with low FAP levels, both grown in mice, were used as controls." (PMID 25633335, 2015). "The radiotracer was successfully produced and accumulated strongly in the FAP-positive SK-Mel-187 melanoma xenograft in vitro while accumulation was negligible in an NCI-H69 xenograft with low FAP levels." (PMID 25633335, 2015). "It has been observed that the expression of FAP-α decreased the tumourigenicity of mouse melanoma cells in animals and restored contact inhibition and growth factor dependence." (PMID 24885257, 2014). "The B16 melanoma model is ideal to evaluate if targeting FAP-positive tumor stroma enhances antitumor effects since B16 cells do not express FAP." (PMID 24349329, 2013). "FAP, also known as Seprase, is a type II transmembrane glycoprotein belonging to the serine protease family and was first isolated from human malignant melanoma." (PMID 19956757, 2009). "The suppression of immunosuppression within the tumor stroma has been shown to enhance the effectiveness of other therapeutic interventions, underscoring the potential of FAPα-targeted therapy as a promising avenue for enhancing outcomes in patients diagnosed with melanoma." (PMID 40918451, 2025). "Specifically, the study revealed that the vaccination of FAPα-expressing B16F10 melanoma cells led to a significant retardation in tumor growth and an enhancement in survival rates of C57BL/6J mice in the experimental group, as compared to the control groups in both experimental studies." (PMID 40918451, 2025). "Furthermore, these α-SMA+ CD90+ FAP+ fibroblasts significantly correlate with survival outcomes in melanoma patients treated with anti-PD-1 antibodies." (PMID 41008624, 2025). "This phase Ib study explored whether the immune cell activation triggered by FAP-IL2v improves the clinical activity of pembrolizumab in patients with anti–PD-1–resistant melanoma." (PMID 39895413, 2025). "Consequently, the FRONTIER study (NCT05432193) investigated the use of this drug in patients with melanoma and other FAPα-positive tumors." (PMID 40918451, 2025).
melanoma (continued). "The 177Lu versions of F19 and A33 mAbs were prepared as control agents, and the potential of the ESC11 and ESC14 radiopharmaceuticals were assessed using SPECT/CT imaging, efficacy studies, and the FAP+ and FAP− melanoma cell lines SK-MEL-187 and SK-MEL-16, respectively." (PMID 40542914, 2025). "In addition to CAFs, ECM components, and previously discussed targets such as CXCR4, FAP, TGF-β, and MMPs, several other TME-associated molecules and pathways have emerged as relevant to melanoma progression and therapy resistance." (PMID 40649909, 2025). "Although mostly studied in other cancers, FAP-targeted radioligand therapy (e.g., 177Lu-FAPi) could theoretically be applied in melanoma stroma-rich lesions." (PMID 41008677, 2025). "Thus, despite previous studies supporting anti-FAPα T-cell responses, this study underscores the limitations of FAPα as a CAR-T therapy target for melanoma and other tumors." (PMID 40918451, 2025). "Furthermore, studies have demonstrated that FAP can be transcriptionally upregulated by the canonical TGF-β pathway using an in vitro model of melanoma." (PMID 38606999, 2024). "Indeed, a whole tumor cell vaccine genetically modified to express FAP significantly reduced cancer growth in a murine model of lung cancer and melanoma by directly inhibiting CAFs and simultaneously enhancing T cell infiltration." (PMID 39516494, 2024). "Although the earliest survey of FAP came from melanoma, the expression and function of FAP in tumor progression remain unclear." (PMID 39055892, 2024). "From the perspective of antibody discovery, ESC11 and ESC14, two antibodies noted for their selective accumulation within xenografted FAP-positive human melanoma and their capacity to impede tumor growth in vivo, were identified in the human FAP antibody library using the phage display technique." (PMID 38543239, 2024). "PD-L1 targets the cell line in A375 melanoma cells transfected with the human PD-L1 gene, whereas the FAP targets are notorious for being ubiquitous in tumor cells, and several clinical trials are underway regarding the diagnostic results of using these two markers." (PMID 37998619, 2023). "In melanoma cells, however, transfection of FAP-α resulted in decreased tumorigenicity." (PMID 36937451, 2023). "FAP is expressed in a large number of cancers, and research in melanoma has shown that FAP is expressed in cancer-associated fibroblasts yet is not expressed in cancer cells themselves." (PMID 36230500, 2022). "In a B16-FAP melanoma model, we found that FAP-IL2v treatment increased CD8+ T cell and NK cell infiltration, which may partly explain the increased tumor uptake of VAP-1-targeted [68Ga]Ga-DOTA-Siglec-9." (PMID 35874707, 2022). "Additionally, a subsequent study from this same group using mouse models of melanoma and lymphoma showed that vaccination of mice with DCs loaded with FAP mRNA reduced primary tumor growth as well as lung metastases." (PMID 34200702, 2021). "Interestingly, only the monospecific FAP-IL is detectable in the low endogenous FAP expressing melanoma model at this time." (PMID 33076292, 2020). "It was found that tumor tissue excised after the 48 h of liposomal nanomedicine administration indicates intense liposomal fluorescence in the case of mice bearing FAP-expressing fibrosarcoma HT1080-hFAP compared to the FAP-expressing human melanoma MDA-MB435S." (PMID 33374391, 2020). "The bispecific Bi-FAP/HER2-IL accumulation and cargo release in both tumor models was gradual and continuous, and caused higher fluorescence signals in the HT1080-hFAP tumor models than the melanoma model." (PMID 33076292, 2020). "Overall these data indicate that in either melanoma model targeting FAP+ tumor stroma cells reduces the content of MDSCs within tumors, which may create a more supportive niche for antigen-specific TILs by reducing their metabolic stress." (PMID 26943036, 2016).
melanoma (continued). "Therefore using an anti-A2B antibody (clone N-19) we verified that FAP positive cells in melanoma tissue express A2BR." (PMID 27590504, 2016). "Furthermore, it was reported that a FAP α vaccine combined with curcumin stimulates FAP α antibody production and CD8+ T cell-mediated killing of FAP α-expressing stromal cells and prolongs the survival of mice implanted with melanoma." (PMID 26985769, 2016). "Further to the cytokines and chemical substances which induce FAPα expression, physical stimulants, including ultraviolet radiation, also induce upregulation of FAPα expression in fibroblasts, melanocytes and primary melanoma cells to facilitate invasion and migration of the cells." (PMID 25593080, 2015). "FAPα was initially identified as a cell surface glycoprotein present on stromal fibroblasts of human epithelial cancers and on the invadopodia of a human malignant melanoma cell line LOX, which exhibits aggressive behaviour in experimental metastasis." (PMID 16507127, 2006). "FAP expression in healthy human skin fibroblasts has not been reported by the human protein atlas (September 2021), but has been reported in skin for activated fibroblasts associated with melanoma and during wound healing." (PMID 34884484, 2021). "The authors showed that, besides the degradation of ECM, an additional role of cathepsins in the melanoma cells may be the activation of TFGβ1, which subsequently promotes the upregulation of fibroblast activation protein-alpha (FAP-α)-mediated cancer cell spreading." (PMID 33809973, 2021). "Therefore, FAP has indicative value and may have future potential in a clinical assay to determine likelihood of survival benefit from anti-PD-1 therapy for melanoma." (PMID 31337426, 2019). "The intriguing role of FAP as a negative prognostic and positive indicative biomarker in melanoma is demonstrated by its positive association with survival outcome of anti-PD-1 treated melanoma patients, and its inverse association with prognosis in the absence of immunotherapy." (PMID 31337426, 2019). "Specifically, this therapy appears less effective in conditions with lower FAP expression, such as melanoma and renal cell carcinoma (RCC), while showing increased effectiveness in conditions with high FAP expression, notably cervical cancer." (PMID 38558814, 2024). "Previously documented markers including FOXP3 (Tregs), CD163 (TAMs), CD33 (TANs), FAP (CAFs), MIA (melanoma), and ALDH1A1 (HNSC), were used for cell-type annotation." (PMID 35812726, 2022). "We validated our findings on the negative prognostic significance of FAP in independent cohorts of patients with high FAP-expressing tumors based on the CCLE, including melanoma and glioma." (PMID 35052475, 2022). "In the present study, the purpose of the novel FAP-IL2v treatment was to increase the infiltration of pro-inflammatory/cytotoxic immune cells (CD8+ T cells, NK cells) into B16 melanoma tumors." (PMID 35874707, 2022). "For example, melanoma-derived EVs stimulated the expression of α-SMA and FAP in embryonic fibroblasts." (PMID 36224527, 2022). "A three-marker panel was used, targeting melanoma-specific (melanA and gp100) and CAF markers (fibroblast-activation protein or FAP)." (PMID 32328671, 2021). "The in vivo image-guided delivery of NIR-fluorescence dye in mice bearing FAP-expressing fibrosarcoma HT1080-hFAP and FAP-expressing human melanoma MDA-MB435S was carried out." (PMID 33374391, 2020). "For this purpose, high HER2 expressing SK-BR3, low HER2 expressing MCF-7, high stable-FAP expressing fibrosarcoma HT1080-hFAP, and the low FAP expressing melanoma cell line MDA-MB435S were used." (PMID 33076292, 2020). "Agents targeting FAP-α, CXCR4/CXCL12, TGF-β, and other signaling in tumor stroma have been under preclinical study or clinical trials for various cancers including melanoma." (PMID 32373541, 2020).
melanoma (continued). "Pretreatment whole tissue sections from 117 melanoma patients treated with anti-PD-1 therapy underwent CAF (Thy1, SMA, FAP) profiling by multiplex immunofluorescence." (PMID 31337426, 2019). "Here, our results indicate that melanoma cell-released exosomes can elevate α-SMA and FAP expression in NIH/3T3 cells, indicating that melanoma cell-released exosomes can also trigger normal fibroblast reprogramming into CAFs." (PMID 30285793, 2018). "In this assay, we used murine melanoma B16F10 cells, Lewis lung carcinoma LL/2 cells and colon carcinoma CT26 cells to generate tumor models to assess the anti-tumor effects of the FAP-modified tumor cells." (PMID 26394925, 2015). "Collectively, these findings underscore the central role of FAPα as a non-enzymatic modulator of the tumor microenvironment in melanoma, facilitating both invasive and angiogenic processes through its signaling functions." (PMID 40918451, 2025). "Therefore, it is plausible that inactivated tumor cells expressing xenogeneic hFAPα stimulated the production of antibodies that cross-react with native FAPα expressed on CAF and host melanoma cells." (PMID 40918451, 2025). "Fibroblast activation protein (FAP)-targeted PET imaging, as well as programmed death ligand-1 (PD-L1)-targeted PET imaging, have recently been shown to be extremely effective in the detection of various malignant cancers, including malignant melanoma." (PMID 37998619, 2023). "The growth curves of B16-FAP melanoma tumors demonstrated that short-term FAP-IL2v treatment did not inhibit tumor growth." (PMID 35874707, 2022). "For example, transfection of mouse melanoma cell lines with non-enzymatically active FAP reduced their tumorigenicity." (PMID 34490078, 2021). "Animals bearing the stable FAP expressing fibrosarcoma (HT1080-hFAP) and the low endogenous FAP expressing melanoma (MDA-MB435S) models were injected with the respective liposomes (20 μmol (lipids)/kg weight) and imaged with the MaestroTM in vivo fluorescence imaging system." (PMID 33076292, 2020). "The novel discovery that FAP is a negative prognostic and positive indicative biomarker in melanoma suggests mechanistic involvement in anti-PD-1 survival advantage." (PMID 31337426, 2019). "Pretreatment whole tissue sections from 117 melanoma patients treated with anti-PD-1 therapy were assessed by multiplex immunofluorescence to detect CAFs defined by Thy1, smooth muscle actin (SMA), and fibroblast activation protein (FAP)." (PMID 31337426, 2019). "Furthermore, a newly developed vaccine that co-targets tumor cells and FAP α, a consistent marker of CAFs, have shown greater antitumor activity with the enhanced induction of infiltration of CD8+ T cells in B16 melanoma models." (PMID 26985769, 2016). "FAPα also enhanced apoptosis in the mouse B16 melanoma cell line independent of DPP4 and its enzymatic activity." (PMID 25593080, 2015). "Seprase (surface expressed protease) or FAPα (fibroblast activation protein α) is a type II transmembrane glycoprotein, originally identified in LOX melanoma cells, contributing to the invasiveness of melanoma and carcinoma cells (for review see:)." (PMID 21674054, 2011). "However, further exploration of FAP-IL2v and pembrolizumab was precluded in patients with melanoma with prior CPI due to the lack of clinical activity." (PMID 39895413, 2025). "According to the data obtained, melanoma cells themselves did not possess FAPα expression." (PMID 40918451, 2025). "Moreover, fibroblasts cultured in the presence of metastatic melanoma secretome exhibited a higher level of FAP-α (in both experimental models—CAFsINS, CAFsCM), and IL6 (only in the case of CAFsCM) in comparison to cells incubated with melanoma cells derived from primary tumors." (PMID 35538545, 2022). "In addition, high levels of FAP expression can be detected in some tumors that are derived from non-epithelial tissues, such as melanoma and myeloma." (PMID 34490078, 2021).
melanoma (continued). "Fibroblast activation protein α (FAPα) vaccine in combination with curcumin was shown to significantly inhibit TNFα-induced EMT in melanoma cells by targeting indolamine-2,3-dioxygenase, inhibit tumor growth and prolong the survival of mice implanted with melanoma cells." (PMID 31547193, 2019). "Similarly, OS had significant positive associations with both Thy1 and FAP cell counts, and a negative association with SMA cell count, which were specific to anti-PD-1 treated melanoma patients (all P < 0.003)." (PMID 31337426, 2019). "Likewise, the mouse melanoma cell line with high levels of stably transformed murine endoglin selectively took up mEnd-IL, but not FAP-IL, LipQ nor the free DY-676-COOH (B16F10-mEnd), which substantiates the target selectivity of the respective immunoliposomes." (PMID 28100205, 2017). "Administration of anti-FAPα CAR-T-cells to the experimental group of mice, it was demonstrated that the antitumor effect on melanoma B16 cells was minimal and did not result in a substantial decrease in tumor mass, likely due to an insufficient tumor stroma." (PMID 40918451, 2025). "The RPMI‐7951 melanoma cell line, which expresses uniformly high levels of FAP, was used for the initial testing of FAP‐CAR‐T cells, while the FAP‐negative U251 glioblastoma cell line was used as a negative control." (PMID 38975278, 2024). "These modifications permitted selection of melanoma cells specifically (e.g., CSPG4-positive, CD45-negative, FAP-negative population)." (PMID 31727958, 2019).